OCSTAMP (osteoclast stimulatory transmembrane protein)
Description:
Probable cell surface receptor that plays a role in cellular fusion and cell differentiation. Cooperates with DCSTAMP in modulating cell-cell fusion in both osteoclasts and foreign body giant cells (FBGCs). Involved in osteoclast bone resorption. Promotes osteoclast differentiation and may play a role in the multinucleated osteoclast maturation (By similarity).
Synonyms: OC-STAMP; C20orf123; dJ257E24.3
Tractability: Antibody: UniProt predicts a signal peptide or a membrane-spanning region.
Gene: Protein-coding gene on chromosome 20 (46,540,946 to 46,550,654, reverse strand). Ensembl gene ENSG00000149635.
Subcellular location: Membrane
Gene Ontology:
Biological process: cellular response to estrogen stimulus; cellular response to tumor necrosis factor; multinuclear osteoclast differentiation; positive regulation of osteoclast differentiation; positive regulation of osteoclast proliferation
Cellular component: membrane
Genetic constraint (gnomAD): Loss-of-function variants: 17 observed, 24.67 expected, observed/expected ratio (o/e) 0.69, 90% interval 0.47 to 1.03. The upper end of that interval is the gene's LOEUF score, 1.03, which puts it in group 4 of 6, group 1 being the genes least tolerant of losing a copy. Missense variants: 605 observed, 629.6 expected, observed/expected ratio (o/e) 0.96, 90% interval 0.9 to 1.03. Synonymous variants: 317 observed, 294.86 expected, observed/expected ratio (o/e) 1.08, 90% interval 0.98 to 1.18.
Homologues: Orthologues: chimpanzee OCSTAMP (99% identical), dog OCSTAMP (69% identical), guinea pig OCSTAMP (63% identical), rabbit OCSTAMP (61% identical), mouse Ocstamp (59% identical), rat Ocstamp (59% identical), pig OCSTAMP (55% identical), tropical clawed frog ocstamp (22% identical), zebrafish ocstamp (20% identical). Paralogues in human: DCST2 (16% identical), DCST1 (16% identical), DCSTAMP (13% identical).
Diseases named in the same sentence as OCSTAMP in open-access papers:
OCSTAMP is named in the same sentence as 7 diseases in open-access papers, as found by Europe PMC text mining. Sharing a sentence is not in itself a finding about the gene and the disease. The quoted sentences say what the papers report.
acute myeloid leukemia (1 paper, 2024). Acute myeloid leukemia (AML) is a group of neoplasms arising from precursor cells committed to the myeloid cell-line differentiation. "One study identified EYA2 as a potential target for molecular therapy in a subtype of acute myeloid leukemia, whereas OCSTAMP mRNA levels were connected to multiple myeloma and TP53RK expression is inversely correlated with multiple myeloma survival." (PMID 38601075, 2024).
OCSTAMP also shares sentences with these, for which no sentence is quoted: blood cancers (1 paper); multiple myeloma (1); myeloid leukemia (1); myeloma (1); osteoporosis (1); silicosis (1).